CAV1 (caveolin 1)
Diseases named in the same sentence as CAV1 in open-access papers (continued):
Sharing a sentence is not in itself a finding about the gene and the disease.
pancreatic cancer (65 papers, 2002 to 2026). "CAV1 is overexpressed in pancreatic cancer, and high levels are associated with worse clinical outcomes, protumorigenic functions, and treatment resistance." (PMID 35158857, 2022). "In pancreatic cancer, the high expression of caveolin-1 (Cav-1) in CAFs was associated with the invasiveness of cancer cells and poor prognosis of patients." (PMID 36185262, 2022). "Cav-1 is highly expressed in fibroblasts and endothelial cells, which are normally implicated in stromal remodeling during pancreatic cancer evolution." (PMID 32377291, 2020). "In the experiments in which Aspc-1 cells were cultured with PSC conditioned medium (CM) or coinjected with PSCs, we showed that Cav-1-deficient PSCs accelerated the growth of pancreatic cancer cells in vitro and in vivo via paracrine shh signaling." (PMID 32377291, 2020). "We found Cav-1 is overexpressed in human PC cell lines, mouse models, and human pancreatic tumors, and is associated with worse tumor grade and clinical outcomes." (PMID 26065715, 2015). "Since JAK2, SOCS, JNK/SAPK, and Src signaling all converge and impinge on STAT3 signaling, our data suggests that loss of Cav-1 serves to reduce pancreatic cancer oncogenic proliferation, migration, invasion, and cell survival through a STAT3 mechanism." (PMID 26065715, 2015). "Higher Cav-1 expression was significantly associated with higher pre-operative CA 19-9 levels (a known poor prognostic marker in pancreatic cancer) by Pearson correlation statistical analysis (r = 0.235, p = 0.04; n = 74)." (PMID 26065715, 2015). "Our results showed that CTCs were detected in 35.71% (5/14) of pancreatic cancer patients with stromal Cav-1 expression versus 77.42% (24/31) of patients with stromal Cav-1 loss." (PMID 24949874, 2014). "Increased CAV1 expression has been reported to be associated with progression of papillary carcinoma of the thyroid, high-grade bladder cancer, poor prognosis of pancreas cancer, and lymph node metastasis in esophageal squamous cell carcinoma." (PMID 22152020, 2011). "Likewise, in esophageal squamous cell carcinoma or pancreatic cancer, CAV1 overexpression is linked to metastasis and worse survival." (PMID 39596307, 2024). "Notably, caveolin-1 overexpression has been associated with radio-resistance in other tumours, like pancreatic cancer, suggesting the potential utility of strategies based on caveolin-1 inhibition to enhance radiotherapy efficacy." (PMID 36482187, 2023). "Our data suggest that Cav-1 deficiency in PSCs is conducive to primary pancreatic cancer growth through upregulated paracrine cytokine signaling (including shh/MMP2/bFGF/IL-6) and that ROS play a vital role in the interaction between PSCs and pancreatic cancer cells." (PMID 32377291, 2020). "Pancreatic cancer cell shh signaling mediates Cav-1-deficient PSC-induced angiogenesis." (PMID 32377291, 2020). "Moreover, Cav-1-deficient PSCs accumulated ROS to enhance the shh pathway and angiogenesis in pancreatic cancer cells." (PMID 32377291, 2020). "Thus, our data suggest that Cav-1-deficient PSCs secrete cytokines that facilitate pancreatic cancer proliferation, invasion, and angiogenesis." (PMID 32377291, 2020). "The loss of stromal Cav-1 expression predicts poor clinical outcomes in pancreatic cancer." (PMID 32377291, 2020). "Therefore, our data suggest that stromal loss of Cav-1 acts as a tumor promotor in pancreatic cancer progression." (PMID 32377291, 2020). "Given the high preponderance of KRAS activating mutations in PC (~90%), we hypothesized whether KRAS mutations could be contributing to the high frequency of Cav-1 expression in pancreatic cancer." (PMID 26065715, 2015). "Given the finding that Cav-1 is overexpressed in pancreatic cancer and is associated with worse outcomes, we determined whether or not caveolae could have a role in promoting pancreatic cancer tumor cell survival and proliferation." (PMID 26065715, 2015).
pancreatic cancer (continued). "Association between stromal Cav-1 expression and clinicopathologic factors in pancreatic cancers." (PMID 24949874, 2014). "The loss of stromal Cav-1 in pancreatic cancer was an independent prognostic indicator, thus suggesting that stromal Cav-1 may be an effective therapeutic target for patients with pancreatic cancer." (PMID 24949874, 2014). "To understand further the stromal Cav-1 protein expression in pancreatic stroma (mostly fibrocytes), we first extracted CAFs from pancreatic cancer cells, paracancer-associated fibroblasts (PAFs), paracancerous tissue, and NFs from non-cancerous partial pancreatectomy specimens." (PMID 24949874, 2014). "In addition, Cav-1 expression was shown to increase in several types of human cancers, including lung, breast, prostate, and pancreas cancers, and this up-regulation was associated with a high degree of metastasis." (PMID 23460862, 2013). "In light of this finding, we suggest that overexpression of wild-type caveolin-1 may be associated with cancer progression in pancreatic carcinoma." (PMID 12402154, 2002). "Therefore, the loss of stromal Cav-1 may be used as a novel biomarker for pancreatic cancer aggressiveness in a select panel of biomarkers." (PMID 24949874, 2014). "Through in vitro cell experiments, we clarified that Na-OHB downregulated CAV1 expression in pancreatic cancer cells, inhibiting the transcription of the CAV1/AMPK/NRF2 downstream ferroptosis-protective genes SLC7A11 and SLC40A1." (PMID 40180904, 2025). "Our findings identify CAV1 as a pivotal molecular link between ketogenic metabolism and ferroptosis in pancreatic cancer." (PMID 40180904, 2025). "Using the classic ferroptosis inducer RSL3, we compared the sensitivity of wild-type, CAV1-overexpressing, and CAV1-knockdown pancreatic cancer cell lines to RSL3." (PMID 40180904, 2025). "Single-cell RNA analysis showed that CAV1 affects the glycolytic activity in pancreatic cancer fibroblasts and is related to the expression of glycolytic enzymes." (PMID 37907864, 2023). "Since CAV1 has been demonstrated to promote pancreatic cancer invasion and metastasis, we would like to check its role in glioma cancer invasion and metastasis." (PMID 37642765, 2023). "The positive feedback transduction of Cav-1-ROS signal promoted the growth of pancreatic cancer and induced matrix-tumor metabolic coupling." (PMID 35651786, 2022). "The key mediators of LIF for the iCAF phenotype and TGFβ for the myCAF phenotype in pancreatic cancer are modulated by CAV1, which would explain the contradictory role of CAV1 in the TME, and the detailed mechanisms require further analysis." (PMID 35045883, 2022). "Caveolin-1 (Cav-1) is the main structural component of the cave, and its disorder occurs in pancreatic cancer and is related to the patient’s prognosis." (PMID 35651786, 2022). "In pancreatic stellate cells, Cav-1 ablation enhanced the growth of pancreatic cancer via Nrf2-induced Shh signaling." (PMID 36556306, 2022). "For example, CAV1 expression in pancreatic cancer cells was found to be positively correlated with cachectic states." (PMID 36233075, 2022). "It has also been reported that Cav-1 induced the EMT process in pancreatic cancer cells by increasing the expressions of plasma membrane bound E-cadherin and β-catenin, leading to tumor metastasis and chemoresistance." (PMID 34168559, 2021). "In our study, both CAV1 and CAV2 were identified as DEGs, but only CAV2 was a prognostic DEG associated with shorter OS in pancreatic cancer patients." (PMID 34078402, 2021). "FOXM1 promotes EMT in pancreatic cancer by directly binding to the promoter region of the caveolin-1 gene and promoting its expression." (PMID 33428593, 2021). "Specifically, Cav-1-silenced PSCs exhibited increased shh expression, which heterotypically activated the shh signaling pathway in pancreatic cancer cells." (PMID 32377291, 2020).
pancreatic cancer (continued). "In pancreatic cancer, knockdown of Cav-1 in fibroblasts led to enhanced tumor growth and chemoresistance." (PMID 32377291, 2020). "We reveal that Cav-1-silenced PSCs facilitated the growth of pancreatic cancer cells via enhanced paracrine shh/MMP2/bFGF/IL-6 signaling." (PMID 32377291, 2020). "In our present study, we show that disruption of the Cav-1 gene accelerated the growth of Aspc-1 pancreatic cancer cells in mice and facilitated Aspc-1 cell invasion." (PMID 32377291, 2020). "Here, we show that coinjection of Cav-1-silenced pancreatic stellate cells (PSCs) with pancreatic cancer cells increased tumor growth." (PMID 32377291, 2020). "In the promoter levels of Cav1, Met, Mylpf, and Lamb3, which were all survival significant factors in pancreatic cancer, TF Rreb1 was discovered to be in the minor view." (PMID 32266133, 2020). "Although the functions of Cav-1 in many tumor cells have recently been elucidated, the role of stromal Cav-1 in pancreatic cancer progression remains less well studied." (PMID 32377291, 2020). "In conclusion, we reveal that ablation of Cav-1 in PSCs promoted the growth, invasion, and angiogenesis of pancreatic cancer." (PMID 32377291, 2020). "Our data revealed that CM from Cav-1-knockdown PSCs increased DNA synthesis and upregulated Gli-1 expression in pancreatic cancer cells." (PMID 32377291, 2020). "CAV1 has been reported to enhance or inhibit various processes in tumor progression, especially as a tumor suppressor in pancreatic cancer cells and NSCLC cells." (PMID 31296840, 2019). "Caveolin-1 can interact with transcription factor Fox M1 to promote epithelial-to-mesenchymal cell transformation and the metastasis of pancreatic cancer cells." (PMID 30424755, 2018). "We chose pancreatitis as a model to study the potential contribution of CAV1-YAP regulation in vivo, because YAP is required for pancreatitis-induced ADM and CAV1 expression is upregulated in pancreatic cancer and it is associated with decreased survival." (PMID 30404014, 2018). "Cav-1 expression was also tested on a tissue microarray of 110 patients with pancreatic cancer, and scored semi-quantitatively for low versus high expression." (PMID 26065715, 2015). "Taken together, while the majority of pancreatic cancers up-regulate Cav-1, the degree of this up-regulation varies between tumors." (PMID 26065715, 2015). "The inverse relationship between Cav1 and Snail-1 was recently confirmed in a model of pancreatic cancer, and the same study also showed the correlation between Cav1 and E-cadherin expression." (PMID 25550395, 2015). "Since the JAK-STAT pathway is an important regulator of cell survival and cytokine receptor signaling, our data suggests that knocking down caveolin-1 affects cell survival and proliferation in pancreatic cancer cells via this pathway." (PMID 26065715, 2015). "Previous studies showed that the re-expression of Cav1 restored the epithelial phenotype by suppressing the EMT signaling pathways in pancreatic cancer cells or reduced the transformation phenotype by blocking c-Src and c-Met tyrosine kinases in osteosarcoma." (PMID 26189182, 2015). "We found that commonly used chemotherapeutics used to treat pancreatic cancer increased Cav-1 expression." (PMID 26065715, 2015). "To determine the prognostic value of stromal Cav-1 for pancreatic cancer, we analyzed the cumulative survival of patients according to their Cav-1 status." (PMID 24949874, 2014). "Our data suggest that miR-203 inhibits cell migration and invasion via caveolin-1 in pancreatic cancer cells." (PMID 24520289, 2014). "In pancreatic cancer, Cav-1 is frequently expressed in the tumor tissue compared with the little or no staining identified in chronic pancreatitis specimens, normal ductal epithelium and peritumoral tissue." (PMID 25202343, 2014). "Stromal Cav-1 was downregulated in pancreatic cancer compared with paraneoplastic and normal tissue." (PMID 24949874, 2014).
pancreatic cancer (continued). "We investigated stromal Cav-1 expression in pancreatic cancer to evaluate a potential role for stromal Cav-1 as a prognostic marker." (PMID 24949874, 2014). "In summary, stromal Cav-1 is downreguated in pancreatic cancer and is closely related to advance TNM stage, lymph node metastasis, and poor prognosis." (PMID 24949874, 2014). "To examine the expression status of stromal Cav-1 in pancreatic cancer, we used immunohistochemistry to evaluate the pancreatic cancer, paraneoplastic, and normal tissue sections." (PMID 24949874, 2014). "Stromal Cav-1 expression was measured from pancreatic cancer, paraneoplastic, and normal tissue using immunohistochemistry." (PMID 24949874, 2014). "This process has demonstrated that Cav1-silenced pancreatic cancer cells seem to be sensitized to ionizing radiation, and this suggests that Cav1 acts as pro-survival factor in the cellular response to ionizing radiation." (PMID 23521716, 2013). "Recently, a direct correlation between Cav1 and FoxM1 expression has been reported in pancreatic cancer cells." (PMID 23521716, 2013). "In the present study, we examined the expression and clinical impact of caveolin-1 in a cohort of patients with pancreatic carcinoma, using immunohistochemical analysis." (PMID 12402154, 2002). "We found that caveolin-1 is overexpressed in pancreatic carcinoma and has a significant prognostic value for patients with this disease." (PMID 12402154, 2002). "This is the first study demonstrating the prognostic significance of caveolin-1 expression in pancreatic carcinoma." (PMID 12402154, 2002). "The GEPIA2 online tool employed to analyze the OS and recurrence‐free survival (RFS) of 30 genes revealed four genes, including CAV1, TMEM43, IQGAP1, and CDK1, that were significantly correlated with pancreatic cancer risk based on their differential expression between tumor and normal tissues." (PMID 40539383, 2025). "In the pancreatic tumor microenvironment, CAV1 was predominantly expressed in tumor cells." (PMID 40180904, 2025). "Previous studies suggested that the expression of CAV1 might act as a bidirectional factor for many malignancies, such as lung, breast and pancreatic cancers." (PMID 36830672, 2023). "Similarly, overexpression of CAV1 in a pancreatic-cancer cell line resulted in less-aggressive phenotypes and attenuated the chemoresistance to doxorubicin." (PMID 35158857, 2022). "Furthermore, our clinical data highlighted the prognostic value of the circFARP1/CAV1/miR-660-3P/LIF axis for predicting GEM resistance in patients with pancreatic cancer." (PMID 35045883, 2022). "Some observations point to Cavin-1 promoting tumor migration in pancreatic cancer cells by cooperating with caveolin-1 but inhibiting invasiveness and metastasis by matrix metalloproteinase 9 (MMP-9) production, neutralizing CAV1 tumor-promoting properties in PC3 pancreatic cancer cells." (PMID 35722492, 2022). "Moreover, the integral membrane protein Cav-1, which induced Akt phosphorylation and β1 integrin upregulation, can promote the radioresistance in 3D pancreatic cancer models." (PMID 34439214, 2021). "Since ROS are involved in the interaction between pancreatic cancer cells and PSCs, we examined whether ROS played a vital role in the observed effects of Cav-1-knockdown PSCs on pancreatic cancer shh signaling." (PMID 32377291, 2020). "However, the function of Cav-1 in the pancreatic cancer microenvironment remains largely unexplored." (PMID 32377291, 2020). "Moreover, for some cancers where CAV1 is highly expressed, such as pancreatic cancer, the tumor cells are highly sensitive to albumin-bound or conjugated chemotherapeutic drugs." (PMID 32458269, 2020). "Also, senescent cancer-associated fibroblasts (CAFs) and, in particular, expression of Caveolin-1 (CAV1) promote tumor invasion in pancreatic cancer." (PMID 32849491, 2020).
pancreatic cancer (continued). "CAV-1 gene endogenous expression or re-expression may also reduce pancreatic carcinoma cell invasion probably through Erk-MMP signal pathway." (PMID 31889941, 2019). "Finally, our data suggests that Cav-1 depletion in pancreatic cancer cells affects various pathways, particularly the JAK/STAT pathway, by decreasing activation of JAK2 and STAT3 and by increasing SOCS2, PIAS3, and DUSP5 inhibitory signals." (PMID 26065715, 2015). "Here, we show that Cav-1 levels in pancreatic cancer could potentially serve as a prognostic biomarker." (PMID 26065715, 2015). "Finally, we demonstrate that targeting Cav-1 through genetic down-regulation in human pancreatic cancer cells can attenuate tumor growth and sensitize tumor cells to chemotherapeutics and radiation." (PMID 26065715, 2015). "We explored roles for Cav-1 in pancreatic cancer (PC) prognostication, tumor progression, resistance to therapy, and whether targeted downregulation could lead to therapeutic sensitization." (PMID 26065715, 2015). "Using human samples, we demonstrate that Cav-1 is a prognostic biomarker in pancreatic cancer." (PMID 26065715, 2015). "Finally, we establish a novel role for Cav-1 in a SOCS-JAK-STAT-SRC signaling pathway in pancreatic cancer cells." (PMID 26065715, 2015). "Our immunohistochemical data also showed lower stromal Cav-1 expression in pancreatic cancer." (PMID 24949874, 2014). "Most importantly, to our knowledge, this study is the first to show that loss of stromal Cav-1 in pancreatic cancer is a negative prognostic indicator." (PMID 24949874, 2014). "To elucidate the function of stromal Cav-1 in pancreatic cancer, we investigated the stromal Cav-1 expression in pancreatic cancer specimens, along with the correlation of stromal Cav-1 expression with tumor marker HER-2/neu and a number of circulating tumor cells (CTCs)." (PMID 24949874, 2014). "This study aims to elucidate whether stromal Cav-1 expression in pancreatic cancer can be a strong prognosis biomarker." (PMID 24949874, 2014). "Following up this result, we searched for this caveolin-1 mutation in 11 pancreatic cancer cell lines, but found no mutation in the predicted functional domains (including the scaffolding and membrane-spanning domain) (data not shown)." (PMID 12402154, 2002). "The multi-level regulatory axis involving CAV1-mediated transcriptional regulation and post-translational modifications provides mechanistic insights into ketogenic diet-induced ferroptosis, suggesting potential therapeutic targets for pancreatic cancer adjuvant treatment." (PMID 40180904, 2025). "However, some studies have insisted that CAV-1 might function as a tumor inhibitor in diverse types of cancer, such as lung, breast and pancreatic cancers." (PMID 36830672, 2023). "Together, our findings show that stromal Cav-1 may mediate different mechanisms in the complex interaction between cancer cells and their microenvironment though Nrf2-induced shh signaling activation during pancreatic cancer progression." (PMID 32377291, 2020). "Most importantly, our in vitro results were corroborated in vivo, as Cav-1 down-regulation markedly attenuated tumor initiation and growth rates in mice, providing direct evidence that Cav-1 is essential for tumorigenicity, growth and proliferation in pancreatic cancer." (PMID 26065715, 2015). "However, stromal Cav-1 expression in pancreatic cancer, as well as its clinical significance, remains unclear." (PMID 24949874, 2014). "Additionally, a series analyzing pancreatic precancerous lesions (pancreatic intraepithelial neoplasia) and a pancreatic cancer survey also indicated that Cav-1 may be a good candidate prognostic marker, combined with the upregulation of fatty acid synthase." (PMID 25202343, 2014).